TACSTD2 (tumor associated calcium signal transducer 2)
Diseases named in the same sentence as TACSTD2 in open-access papers (continued):
Sharing a sentence is not in itself a finding about the gene and the disease.
tumor (continued). "We compared TACSTD2 mRNA expression as reported by the TCGA KIRC data in tumor adjacent normal and paired tumoral tissue and found lower levels of TACSTD2 mRNA in tumoral tissues (p < 0.001, paired t-test)." (PMID 33882870, 2021). "Different findings in various tumor entities nevertheless emphasize the necessity for further detailed analyses of the functional context of TACSTD2 as well as additional epigenetic mechanism possibly relevant for TACSTD2 function." (PMID 33882870, 2021). "The most frequently differentially hypomethylated CpG islands different between the normal and tumor tissues were TACSTD2, followed by SIM2 and DAPK1." (PMID 31675985, 2019). "Although the levels of TACSTD2 expression in Huh7.5 cells were higher than in primary tumor tissue, they were below the threshold of detection by conventional Western blot and immunofluorescence." (PMID 29538454, 2018). "Clu+Tacstd2+Sca-1+ luminal epithelial progenitor cells were identified as candidate tumor initiating cells." (PMID 26807730, 2016). "We studied the initial stages of hyperplasia in the PSA-Cre targeted Pten knockout model and identified Clu+Tacstd2+Sca1+ luminal epithelial progenitor cells as candidate tumor initiating cells." (PMID 26807730, 2016). "The process starts with targeted bi-allelic inactivation of Pten in the prostate where the Clu+Tacstd2+Sca1+ luminal epithelial progenitor cells were identified as candidate tumor initiating cells." (PMID 26807730, 2016). "The present study aimed to retrospectively investigate TACSTD2 antigen expression by immunohistochemistry, in paraffin-embedded primary tumor tissue samples from a series of consecutive SACC patients (n=81)." (PMID 25202389, 2014). "The results were consistent with the previously known functions of TACSTD2 in tumor development and metastasis." (PMID 25202389, 2014). "The present study therefore aimed to retrospectively investigate TACSTD2 protein expression by immunohistochemistry on paraffin-embedded primary tumor tissue samples from a series of consecutive SACC patients (n=81)." (PMID 25202389, 2014). "Trop-2 is a transmembrane glycoprotein receptor encoded by the TACSTD2 gene, which allows for calcium signal transduction intracellularly, playing a role in tumor progression." (PMID 40723191, 2025). "Additionally, in the GSE81538 dataset (n = 250), a significant correlation between high levels of TACSTD2 with low tumor grade (P = .008), low Ki67 (20% cutoff, P = .0008), low pleomorphism (P = .026), and low mitosis (P = .012)." (PMID 40579360, 2025). "Moreover, we found that serum sEVs from the elderly (especially those with high TACSTD2 levels) promoted tumor cell (SW480, HuCCT1 and HeLa) proliferation and migration." (PMID 38698420, 2024). "In tumor cells, AKT signaling shows strong correlation with Tacstd2 expression but MAPK/ERK, ErbB, TGFβ, Wnt/β-catenin, JAK/STAT, and integrin signaling have all been implicated as downstream targets of Tacstd2." (PMID 39666736, 2024). "Similarly, we found that senior serum sEVs, especially those from serum with high TACSTD2 levels, promoted tumor cell proliferation and migration." (PMID 38698420, 2024). "The Box plot confirmed higher TACSTD2 expression in tumor tissues." (PMID 38302503, 2024). "TACSTD2 hypermethylation was associated with a shorter RFS of patients and demonstrate statistical independency from clinical parameters as state of metastasis, tumor stage, grade and state of advanced disease." (PMID 33882870, 2021). "However, while the overexpression of TACSTD2 has been described in several cancer types, conflicting reports abound, with functional studies showing not only oncogenic but also tumor suppressor roles." (PMID 34439112, 2021). "To assess the potential usefulness of TACSTD2 loci methylation we compared relative methylation values in dichotomized tumor groups using bivariate logistic regression including age as a covariate to control a potential bias due to age related methylation effects." (PMID 33882870, 2021).
tumor (continued). "Conversely, TACSTD2 gene expression was the lowest in the metastatic samples, compared with the normal or tumor samples (metastatic vs. normal: 1.39-fold, p = 5.77 × 10−2; metastatic vs. tumor: 0.72-fold, p = 1.09 × 10−1)." (PMID 34439112, 2021). "Here, we investigated whether methylation of TACSTD2 gene loci in RCC associate with clinical parameters of tumor aggressiveness and recurrence free survival (RFS) of patients and identified hypermethylated TACSTD2 loci as a potential prognosticator for RCC." (PMID 33882870, 2021). "PC2 (driven by Ptgs2, Ptges, Inhba, Tacstd2, and Nfat5) could help distinguish between tumor and healthy, although in the Parsortix samples, healthy falls between the two tumor conditions on the PC1 axis." (PMID 35153760, 2021). "A unique feature of our study is that the clinical and biological relevance of TACSTD2 as a regulator of HCV entry is corroborated by a series of in vivo observations that we made in primary tumor tissue obtained at the time of liver explant or resection from well-characterized patients with HCC." (PMID 29538454, 2018). "Downregulation of TACSTD2 reportedly stimulates tumor growth." (PMID 26039047, 2015). "The signaling mechanism of TACSTD2 involved in tumor pathogenesis was first explained by activating the extracellular signal regulated kinase (ERK)/mitogen-activated protein kinase pathway, and cyclin D1 was activated as an important downstream factor of the pathway." (PMID 25202389, 2014). "Additionally, the present findings suggested that exosomal TACSTD2 may contribute to tumour proliferation and metastasis by enhancing glycolysis in OC cells." (PMID 41331197, 2025). "An analysis of the mutations that developed after treatment demonstrated a tumor subclone harboring mutations of TOP1 (which encodes topoisomerase-1, the target of the SG payload), along with a distinct subclone harboring a mutation of TACSTD2 (which encodes TROP2, the antigen target of SG)." (PMID 36831621, 2023). "Interestingly, Tacstd2, the gene encoding the TROP2 protein that is associated with transition to dysplasia but also expressed in some normal tissues, was highly upregulated in the squamous cell population as well as in AOM/DSS tumor cells." (PMID 35600339, 2022). "The present study speculated that TACSTD2 may also function in tumor formation and development." (PMID 25202389, 2014). "In neuroendocrine prostate cancer, TACSTD2-driven AKT1 and c-Myc activation enhances lineage plasticity and tumor progression." (PMID 41331197, 2025). "The last decade has been characterized by the increased evaluation of the biomolecular role of the 40 kDa tumor-associated calcium signal transducer 2 (TACSTD2, also known as trophoblast cell surface antigen 2, TROP2) in tumor initiation and progression." (PMID 34439112, 2021). "We also detected other epigenetically regulated genes in this signature, including CD70, IRAK, IL20RA, THBD, TACSTD2, and MST1R, with implications related to the tumor immune microenvironment." (PMID 34150764, 2021). "Of the 16 tumor-normal pairs with presumed hypermethylated promoter loci in HCC (in genes BMP4, RASSF1,GSTP1, and TACSTD2), 5, 6, 14 and 16 of the 16 HCCs had decreased expression of the gene, respectively." (PMID 23437062, 2013). "Five hypermethylated loci harbored by four genes (GSTP1, TACSTD2, BMP4 and RASSF1) and three hypomethylated loci in three genes (ARHGAP8, GPR35 and DLGAP1) were validated using 7 assays with 12 tumor-normal tissue pairs from this study." (PMID 23437062, 2013). "As expected, there was an enrichment of the H3K4me3 code at the TACSTD2 promoter of tumor tissue when compared to adjacent non-tumor tissue." (PMID 38302503, 2024).
tumor (continued). "Analysis of the residual malignant tumor cells revealed notably higher CD73 expression in the highly resistant subgroup and extensive TACSTD2 (TROP2) expression, which would also enlighten the study design of an ADC combination strategy as a perioperative setting for EGFR-mutant NSCLC." (PMID 38897205, 2024). "Similarly, relative to that between TACSTD2 expression and tumor-infiltrating CD8+ T cells, we found a 1.26-fold higher correlation between GSE1 expression and tumor-infiltrating CD8+ T cells." (PMID 34439112, 2021). "Among all known host factors reported to date that regulate cellular proteins important for HCV entry, TACSTD2 was the only one to be differentially expressed between tumor and surrounding nontumorous tissue." (PMID 29538454, 2018). "In a recent study using a machine learning approach and various algorithms on a set of microarray data obtained from tumor and nontumorous liver specimens, TACSTD2 was found to be downregulated in the tumor versus nontumorous samples." (PMID 29538454, 2018). "The decreased expression of TACSTD2 within the tumor compared to the surrounding nontumorous areas was confirmed by real-time PCR." (PMID 29538454, 2018). "Furthermore, we demonstrated that ZIC1 can suppress the expression of other novel genes (TACSTD2, ANGPT2, LAMB2, LAMB3 and MALAT1 etc.)related to tumor angiogenesis and metastasis." (PMID 21347233, 2011). "Interestingly, the cells positive for Tacstd2 formed clusters in the tumor including glandular structures labeled with Defa6-iCre; however, the scattered Defa6-tdTom cells were predominantly Tacstd2-negative." (PMID 40221753, 2025). "Finally, this analysis was performed for three pairs of tumor and corresponding adjacent non-tumor tissue with high TACSTD2 expression." (PMID 38302503, 2024). "Next, the TACSTD2 expression of tumor and adjacent non-tumor tissues were analysed." (PMID 38302503, 2024). "Whether TROP2-negative tumor cells with TACSTD2 promoter methylation might present resistant cell populations under TROP2 inhibitor treatment with the TROP2-based ADC sacituzumab govitecan needs to be further investigated." (PMID 38302503, 2024). "Furthermore, in primary HCC tumor tissue we found no alteration in the expression of EMT markers compared to the surrounding nontumorous tissue, in spite of the significant reduction of HCV RNA and downregulation of TACSTD2." (PMID 29538454, 2018).
cancer (280 papers, 2004 to 2026). A tumor composed of atypical neoplastic, often pleomorphic cells that invade other tissues. "Tumor-associated calcium signal transduction protein 2 (TACSTD2), which is generally highly expressed in tumors and cancer cells, is also found in embryos; however, reports on its association with spermatogenesis and sperm function are scarce." (PMID 39765560, 2024). "Hypermethylation of the TACSTD2 gene, which encodes Trop2, can silence its expression, contributing to its downregulation in some cancer types." (PMID 39236081, 2024). "The significant strength of this study lies in the cohort size and pan-cancer comparison of TACSTD2 associations." (PMID 38986529, 2024). "In the present study, we explored the genomic, transcriptomic, and immunologic landscape associated with TACSTD2 gene expression in several solid tumor types using a real-world cancer cohort of 36 717 patients." (PMID 38986529, 2024). "TACSTD2 (Trophoblast Cell Surface Antigen 2) has been reported to be associated with malignant tumors." (PMID 38816411, 2024). "Trop2, also known as human tumor-associated calcium signal transducer 2 (Tacstd2), is a surface glycoprotein upregulated in various cancer cells." (PMID 33614493, 2020). "Trop2 is a transmembrane glycoprotein encoded by the Tacstd2 gene and its overexpression is found in several types of cancer." (PMID 33614493, 2020). "TACSTD2 is overexpressed in many cancers and has been associated with disease progression, migration, recurrence, and increased proliferation." (PMID 30002602, 2018). "Mounting evidence has showed that Tumor-associated calcium signal transducer 2 (Trop2) is upregulated in various kinds of human cancers and plays important roles in tumorigenesis." (PMID 28709407, 2017). "Bamodu O.A., Wang Y.H., Ho C.H., Hu S.W., Lin C.D., Tzou K.Y.,Wu W.L., Chen K.C., Wu C.C. Genetic suppressor element 1 (GSE1)promotes the oncogenic and recurrent phenotypes of castration-resistantprostate cancer by targeting tumor-associated calcium signaltransducer 2 (TACSTD2)." (PMID 36923483, 2023). "TACSTD2 encodes a transmembrane glycoprotein Trop2 commonly overexpressed in carcinomas." (PMID 35688908, 2022). "TACSTD2, a calcium signal transducer implicated in the pathogenesis of several other tumors, was a newly identified potential biomarker, as it was almost exclusively expressed by cancer cells." (PMID 33803085, 2021). "One of the genes identified, tumor associated calcium signal transducer 2 (TACSTD2), is altered by DNA methylation, and there is evidence that in some cancers decreased expression may result in greater proliferation." (PMID 30002602, 2018). "Although TACSTD2 has been reported to be associated with cancer, the regulatory mechanism of TACSTD2 remains unclear." (PMID 22053771, 2011). "Given its overexpression in most cancer tissues, TACSTD2 is an attractive target for cancer therapy." (PMID 41331197, 2025). "TROP2 (also known as TACSTD2) is a transmembrane receptor that can be aberrantly expressed in several cancers." (PMID 38927637, 2024). "Of all the cancer types, TACSTD2-high urothelial cancer demonstrated the most significant pattern of lower immune cell infiltration, with a smaller fraction of M1 macrophages, dendritic cells, Tregs, CD8+ T cells, and B cells (P < .05)." (PMID 38986529, 2024). "TACSTD2 is highly expressed in many cancers, and exhibits differential expression in certain normal tissues." (PMID 38817863, 2024). "Human trophoblast cell surface glycoprotein antigen (TROP-2), also known as tumor-associated calcium signal transducer 2 (TACSTD2), is the protein product of the TACSTD2 gene, a type I cell surface glycoprotein highly expressed in human cancers." (PMID 38194043, 2024). "In total, nine inflammation and cancer-associated DEGs were selected to show their changed expression patterns, comprising four up-DEGs (ADM, FSTL3, SPDEF, and SPNS2) and five down-DEGs (TACSTD2, CCL2, EDIL3, FAM20C, and OLFML2A)." (PMID 37953789, 2023).
cancer (continued). "No connections of these clusters with GRHL2 were visible but the interaction of GRHL2 with CLDN4 was shown as well as co-expression of GRHL2 with TACSTD2, a transmembrane receptor regulating cell proliferation and migration in development and cancer." (PMID 36691073, 2023). "Tumor-associated calcium signal transducer 2 (TROP2) is overexpressed in many epithelial cancers including CCA and TROP2 corelates with a poor prognosis in various cancers." (PMID 36405499, 2021). "Although TACSTD2 was found to be highly expressed in many cancer types, only a few very recent reports are available about its functional role in cancer." (PMID 31772156, 2019). "The TACSTD2 protein plays an important role as an adhesion receptor between cancer cells and as a calcium signal transducer." (PMID 31534795, 2019). "Despite the discrepancies, the evidence for over-expression of TACSTD2 in cancer is sufficiently compelling to support clinical trials targeting membrane TROP2." (PMID 30002602, 2018). "TROP2 (also known as TACSTD2) is a transmembrane glycoprotein that is highly expressed in many cancers, and is a promising molecular target for the treatment of various malignancies." (PMID 28486396, 2017). "Specifically, serologically defined colon cancer antigen 1 (SDCCAG1) and tumor-associated calcium signal transducer 2 (TACSTD2) are defined by their presence and association with cancer." (PMID 25751518, 2015). "Retrospective studies have found that overexpression of TACSTD2 predicts poor prognosis in the majority of human cancers." (PMID 25202389, 2014). "The prostate basal cells and hepatic oval cells, considered progenitor cells, show HIGH expression of the TACSTD2 gene and maintain self-renewal capability, and thereby implicating a potential role of TACSTD2 in cancer initiating stem cells." (PMID 22053771, 2011). "Among represented gene in E0, TACSTD2 has been confirmed to be highly expressed in various cancers." (PMID 38817863, 2024). "Levels of proteins Rngtt, Rp1l1, Tacstd2, Zfyve26, and Zfyve27, which are known to promote a proliferative phenotype in various cancers, were decreased in the brain vasculature of TGF mice, likely as an attempt to attenuate vascular proliferation and remodeling." (PMID 38132326, 2023). "The gene encoding Trop-2 is Tacstd2, which, while not a cancer gene itself, is correlated with cancer." (PMID 38352694, 2023). "Moreover, methylation comparison between localized and advanced cancers revealed that tumors classified as advanced disease showed higher mean methylation at TACSTD2 loci (p < 0.001, OR = 1.20, 95% CI: 1.08–1.34)." (PMID 33882870, 2021). "Furthermore, we and others showed that Trop2 expression is regulated by methylation of TACSTD2 gene promoter in various cancer cells." (PMID 33187148, 2020). "Indeed, TACSTD2 (associated with good prognosis) was only significantly higher in expression in the CR and PR cancer-stromal doublets over their cancer cells and fibroblast singlet counterparts, but not the PD group." (PMID 40280979, 2025). "However, there also is evidence of decreased TACSTD2 expression in cancer." (PMID 30002602, 2018). "The results indicated that TACSTD2, ENTPD1, and SERPINA1 have some predictive ability for other cancer types, such as ATC and FTC, but their predictive power is not as strong as it is for PTC." (PMID 40520228, 2025). "Several genes such as CXCR4, APQ1, TACSTD2, and S100A9 have been reported to participate in angiogenesis or are highly expressed in endothelial cells in cancer." (PMID 37626402, 2023). "Among all cancers in The Cancer Genome Atlas (TCGA), HNSC harbors the third highest median TACSTD2 expression levels (265.2 fragments per kilobase million (FPKM0))." (PMID 37835579, 2023). "However, no mutations in TACSTD2 have been reported in cancer." (PMID 29989029, 2018).
cancer (continued). "Although mild expressions were demonstrated in total cancer cell cluster C1 and C8 in non‐recurrent group, the CLDN4 expression along with ELF3, TACSTD2 and EpCAM could only be seen in recurrent cells of total C1." (PMID 38629624, 2024). "Tacstd2 has not been studied in relation to kidney disease but has been the subject of extensive research in cancer where it has been found have high expression in many solid tumors with little expression in normal tissues." (PMID 39666736, 2024). "In the ground of methylation, one hyper-methylated/under-expressed gene (CA12) and two hypo-methylated/over-expressed genes (COL1A1, and TACSTD2) were found which were confirmed both by expression (only by the validation dataset) and methylation (by MEXPRESS in two COAD, and READ cancer types)." (PMID 35333898, 2022). "While TACSTD2 has not been studied in PKD, it has been studied in cancer where it is highly expressed in solid tumors while showing minimal expression in normal tissue." (PMID 39666736, 2024).